NGF (nerve growth factor)
Diseases named in the same sentence as NGF in open-access papers (continued):
Sharing a sentence is not in itself a finding about the gene and the disease.
vitamin D deficiency (3 papers, 2011 to 2023). A nutritional condition produced by a deficiency of VITAMIN D in the diet, insufficient production of vitamin D in the skin, inadequate absorption of vitamin D from the diet, or abnormal conversion of vitamin D to its bioactive metabolites. "In rats, the production of nerve growth factor which is required for the development and survival of both sympathetic and sensory neurons decreases in the presence of vitamin D deficiency." (PMID 23304571, 2012). "Animal studies have shown that vitamin D deficiency is associated with low levels of neurotrophins (especially nerve growth factor) and defective neuronal calcium homeostasis." (PMID 23304571, 2012). "In our study, NGF down-regulation was observed when VDR was silenced; this may provide a molecular explanation for previous in vivo results demonstrating that animals exposed to transient-early vitamin D deficiency had reduced NGF protein levels." (PMID 21408608, 2011). "Moreover, animals that have a transient-early vitamin D deficiency have relatively large lateral ventricles, reduced NGF protein and reduced expression of a number genes involved in neuronal structure." (PMID 21408608, 2011). "Furthermore, we speculate that some of the toxic effects induced by Aβ, including disruption of calcium homeostasis and dysregulation of NGF synthesis, may be caused by vitamin D deficiency and/or the inefficient utilization of vitamin D due to VDR protein depletion." (PMID 21408608, 2011). "With NGF another mediator of visceral hypersensitivity was identified in our IPA analysis, which additionally revealed vitamin D deficiency as a factor in susceptibility to IBS-M and proposed curcumin and quercetin as potential functional foods for IBS-M patients." (PMID 36672170, 2023).
abortion (2 papers, 2011 to 2017). the ending of pregnancy by removing a fetus or embryo before it can survive outside the uterus. "The abortion risk may be explained by the decreased levels of Nerve Growth Factor (NGF)." (PMID 29066809, 2017). "NGF also has a relationship with uterine weight and participates in stress-triggered and substance P-mediated abortion." (PMID 21385399, 2011).
ameloblastoma (2 papers, 2020 to 2024). The most common odontogenic tumor, arising from the epithelial component of the embryonic tooth and usually affecting the molar-ramus region of the mandible or maxilla. "P75/NGFR was expressed at high levels throughout the ameloblastoma epithelium, as well as in stromal regions associated to NGF expression." (PMID 32155948, 2020). "We have shown that the ameloblastoma epithelium expresses detectable levels of the neurotrophins NGF and BDNF, as well as the neurotrophin receptors TRKA, TRKB, and P75/NGFR." (PMID 32155948, 2020). "Taken together, our results show that ameloblastomas exhibit stem cell potential, express NGF, BDNF, and neurotrophin receptors, and create contacts with trigeminal neurons that might play key roles in the onset and progression of these tumors." (PMID 32155948, 2020). "Additionally, we showed that ameloblastomas express the neurotrophic factors NGF and BDNF, as well as their receptors TRKA, TRKB, and P75/NGFR, which are responsible for their innervation by trigeminal axons in vivo." (PMID 32155948, 2020). "The NGF signal could also be detected within the ameloblastoma epithelium, in particular in cells located in proximity to the underlying stroma (yellow arrowheads)." (PMID 32155948, 2020). "Using immunofluorescent staining, we detected expression of the neurotrophins NGF (Nerve Growth Factor) and BDNF (Brain Derived Neurotrophic Factor), as well as their receptors P75/NGFR, TRKA and TRKB, in human ameloblastoma biopsies." (PMID 32155948, 2020).
anxiety disorder (2 papers, 2014 to 2022). A category of psychiatric disorders which are characterized by anxious feelings or fear often accompanied by physical symptoms associated with anxiety. "Using an adjusted linear regression analysis, PPAD (p = 0.049), maternal anxiety disorder (p = 0.043), NGF level (p = 0.034) and infant cortisol level (p = 0.013) were associated with infant motor development." (PMID 24733087, 2014). "Linear regression of infant neurobiological - motor development (AIMS Score) and: history of affective disorders, postpartum affective disorder (PPAD), maternal anxiety disorder, maternal NGF levels and infant cortisol levels." (PMID 24733087, 2014).
autonomic dysreflexia (2 papers, 2015 to 2022). A syndrome associated with damage to the spinal cord above the mid thoracic level (see SPINAL CORD INJURIES) characterized by a marked increase in the sympathetic response to minor stimuli such as bladder or rectal distention. "Furthermore, efforts to block the effects of NGF, Wnts, and PI3K are effective at preventing the development of neuropathic pain and autonomic dysreflexia." (PMID 26093674, 2015).
channelopathy (2 papers, 2022 to 2025). Channelopathies are a group of diseases caused by the dysfunction of ion channel subunits or their interacting proteins. "Furthermore, the current authors suggest that the nerve growth factor (NGF)-tropomyosin receptor kinase A (TrkA) axis signaling plays a role in promoting the development of this dose-limiting and threshold-driven Piezo2 channelopathy that may explain the sex difference in the epidemiology of DED." (PMID 35507012, 2022).
chronic asthma (2 papers, 2013 to 2021). An asthma that is characterized by the development of persistent airway inflammation and recurrent attacks of breathlessness and wheezing, which vary in severity and frequency. "Therefore, prior to evaluating the effects of NGF, we first examined whether NGF levels increased following repeated antigen challenge in our chronic asthma model." (PMID 24223654, 2013).
CIP with (2 papers, 2023 to 2024). "The central role of TrkA and NGF in pain is evident in patients with hereditary sensory and autonomic neuropathy (HSAN) types IV and V, where pathological insensitivity to pain results from loss-of-function mutations in TrkA and NGF, respectively." (PMID 39589827, 2024).
diabetic foot ulcers (2 papers, 2017 to 2025). "Animal studies have indicated the ability of human UCB-MSCs to prevent or cure DFU via angiogenesis and the expression of nerve growth factor (NGF) in femoral nerve innervated gastrocnemius of diabetic foot ulceration rats." (PMID 28386568, 2017).
encephalopathies (2 papers, 2022 to 2023). "We therefore focused on fetal OPCs, with the aim of establishing whether NGF protects these cells in a well-described model of OGD, one which mimics the HI and reoxygenation/reperfusion occurring in neonatal encephalopathies." (PMID 36875668, 2023).
essential hypertension (2 papers, 2022 to 2025). Hypertension that presents without an identifiable cause. "First, the causal relationship between enhanced NGF status and sympathoadrenal hyperactivity in primary hypertension cannot be deduced from our study, because this study was a cross-sectional study." (PMID 35284140, 2022). "Although more studies are warranted to solve the issues listed as study limitations, the clinical implication of this study is that enhanced NGF status could be possibly postulated as one of the causes of sympathetic overactivity in primary hypertension." (PMID 35284140, 2022). "Our data indicate that enhanced NGF status and subsequent NGF-induced sympathoadrenal overactivity could occur in primary hypertension." (PMID 35284140, 2022). "Thus, the enhancements of both NGF status and sympathoadrenal activity and the positive relationships between them were characteristic phenomena for primary hypertension." (PMID 35284140, 2022). "Accordingly, it might be hypothesized that in primary hypertension, the feedback regulation of NGF synthesis by sympathetic influences could be more positive due to the greater alpha-receptor activation." (PMID 35284140, 2022). "Accordingly, our data indicated that in primary hypertension, NGF status could be enhanced and subsequent NGF-induced sympathoadrenal activation might occur in proportion to the degree of NGF status." (PMID 35284140, 2022). "This notion might explain the positive relationship between NGF and catecholamines found in primary hypertension." (PMID 35284140, 2022). "Thus, primary hypertension was characterized by the enhancements of both NGF status and sympathoadrenal activity and the positive relationship between them." (PMID 35284140, 2022). "Although limited for these reasons, the present study showed that the enhanced NGF status and subsequent NGF-induced sympathoadrenal overactivity could occur in primary hypertension." (PMID 35284140, 2022). "Second, the renin-angiotensin system might be considered as another modulator for NGF production in primary hypertension." (PMID 35284140, 2022). "This hypothesis is supported by the observation that NGF mRNA and/or protein increase in the sympathetic innervated organs such as the blood vessels, heart, and kidneys of spontaneously hypertensive rats (SHRs), an animal model of human primary hypertension." (PMID 35284140, 2022).
facial nerve paralysis (2 papers, 2015 to 2025). "Considering that no other systematic study of NGF as a facial palsy treatment is available, it was not possible to compare the results of the present study with other meta-analyses." (PMID 25574223, 2015).
Fanconi anemia (2 papers, 2024 to 2025). Fanconi anemia (FA) is a hereditary DNA repair disorder characterized by progressive pancytopenia with bone marrow failure, variable congenital malformations and predisposition to develop hematological or solid tumors. "The most significant SNP on chromosome 26 was located between NGF and FANCE; NGF is known to be involved in nerve growth, while FANCE plays a key role in the Fanconi anemia pathway." (PMID 40427243, 2025).
fatty liver disease (2 papers, 2019 to 2021). A reversible condition wherein large vacuoles of triglyceride fat accumulate in liver cells via the process of steatosis. "Likewise, NGF was elevated in leptin-receptor-deficient db/db mice, used as another model for fatty liver disease." (PMID 31296846, 2019). "It was also demonstrated in a mouse model of fatty liver disease that NGF and p75NTR were upregulated." (PMID 34064584, 2021).
fibrosarcoma (2 papers, 2014 to 2025). A malignant mesenchymal fibroblastic neoplasm affecting the soft tissue and bone. "Mitochondrial STAT3 has been linked directly to increased ROS generation in at least two distinct signaling contexts: TNF-α-mediated necroptosis in L929 mouse fibrosarcoma cells and NGF-dependent neurite outgrowth in PC12 cells." (PMID 24671708, 2014).
frontotemporal dementia (2 papers, 2022 to 2025). Frontotemporal dementia (FTD) comprises a group of neurodegenerative disorders, characterized by progressive changes in behavior, executive dysfunction and language impairment, as a result of degeneration of the medial prefrontal and frontoinsular cortices. "Clinical: The efficacy of NGF as an IN therapeutic was investigated in two female patients with frontotemporal dementia (FTD) associated with corticobasal syndrome (FTD/CBS)." (PMID 36429060, 2022).
functional dyspepsia (2 papers, 2019 to 2023). "Nerve growth factor (NGF) and enteric glial cells (EGCs) are associated with visceral hypersensitivity and gastrointestinal motility disorder, which may represent the pathogenesis of functional dyspepsia (FD)." (PMID 31856738, 2019).
insomnia (2 papers, 2019 to 2025). A sleep disorder characterized by difficulty in falling asleep and/or remaining asleep. "Additionally, BDNF and NGF concentrations were significantly augmented in the observation group, emphasizing the therapeutic potency of the formula for IS patients experiencing insomnia due to qi deficiency and blood stasis." (PMID 40760550, 2025).
intracerebral hemorrhage (2 papers, 2011 to 2015). A cerebrovascular disorder characterized by bleeding into one or both cerebral hemispheres including the basal ganglia and the cerebral cortex. "The present study was aimed to investigate the effects of minocycline (MC) on the expression of nerve growth factor (NGF) and heat shock protein 70 (HSP70) following intracerebral hemorrhage (ICH) in rats, and explore the neuroprotective function of MC." (PMID 23554704, 2011).
limb ischemia (2 papers, 2014 to 2024). A ischemia that involves the limb. "It has been suggested that supplementation of NGF promotes angiogenesis in mice with limb ischemia through a VEGF-dependent mechanism." (PMID 25006578, 2014).
lung adenocarcinoma (2 papers, 2016 to 2022). A carcinoma that arises from the lung and is characterized by the presence of malignant glandular epithelial cells. "In lung adenocarcinomas, the expression and role of the NGF/TrkA system has been demonstrated." (PMID 36289793, 2022). "To identify relevant published data on NTs and NT receptors in lung adenocarcinoma, we conducted a literature search on PubMed using the following keywords: neurotrophins, NT receptors, nerve growth factor, Brain-Derived Neurotrophic Factor, NT-3, lung adenocarcinoma, and human”." (PMID 36289793, 2022).
lung squamous cell carcinoma (2 papers, 2018 to 2023). "From a clinical perspective, our data suggest that anti-TrkA therapies may be more effective in squamous cell lung cancer and could eventually be associated with NGF targeting." (PMID 29802376, 2018). "The regulatory mechanism that controls proNGF processing is poorly described in cancer, but our data suggest that proNGF is largely processed into NGF in squamous cell carcinomas of the lung." (PMID 29802376, 2018). "In contrast to NGF, proNGF was only slightly increased in squamous cell lung cancer and adenocarcinoma." (PMID 29802376, 2018). "In conclusion, these data suggest a preferential therapeutic value of targeting the NGF-TrkA axis in squamous cell carcinomas of the lung." (PMID 29802376, 2018). "Although further functional investigations are warranted to test this hypothesis, our data reveals that TrkA and its ligand NGF are overexpressed in squamous cell lung cancer." (PMID 29802376, 2018). "Interestingly, NGF was also increased in squamous cell lung cancer and to a lesser extent in adenocarcinoma." (PMID 29802376, 2018). "MAP3K14 has been found to be differentially expressed and hypermethylated in lung squamous cell carcinoma, where it regulates the NF-κB activity pathway and participates in NF-κB-inducing signaling through receptors of the tumor-necrosis/nerve-growth factor (TNF/NGF) family." (PMID 37628872, 2023).
lymphoma (2 papers, 2016 to 2017). A malignant (clonal) proliferation of B- lymphocytes or T- lymphocytes which involves the lymph nodes, bone marrow and/or extranodal sites. "Upon serum deprivation, exogenous NGF was capable of promoting the viability and proliferation of the lymphoma cells." (PMID 28557340, 2017). "NGF effectively salvaged the serum‐depleted lymphoma cells by increasing their viability and proliferation in a concentration‐dependent manner." (PMID 28557340, 2017). "Although, according to the manufacturer, the ELISA kit detects both the pro‐ and active forms of NGF, the data support autocrine secretion of NGF by the lymphoma cell lines compared with human T lymphocytes that appear to release much lower levels." (PMID 28557340, 2017). "Likewise, the expression of NGF was upregulated in the lymphoma cell lines, with much lower levels in the T cells." (PMID 28557340, 2017). "In addition, in our hands, exogenous NGF and conditioned medium from the lymphoma cells increased, albeit slightly, basal levels of phosphorylation of TrkA." (PMID 28557340, 2017). "Whereas these results suggest that the lymphoma cells secrete the active form of NGF, phosphorylation of TrkA appears to be more dependent on NPM‐ALK and to a lesser extent on NGF." (PMID 28557340, 2017).
male infertility (2 papers, 2022 to 2024). The inability of the male to effect fertilization of an ovum after a specified period of unprotected intercourse. "Some studies were conducted to investigate the possible role of NGF in the management of male infertility." (PMID 36361912, 2022). "Further studies are required to reach a better understanding of the involvement of NGF in male reproductive system pathophysiology and, hence, its potential role in the management of male infertility." (PMID 36361912, 2022). "However, more studies need to be carried out to understand the precise mechanisms of NGF actions in male infertility management and its use in assisted reproductive technologies." (PMID 38792459, 2024). "Furthermore, it is crucial to expand our knowledge of NGF’s role in pathologic conditions of the male reproductive system and optimize its therapeutic use for male infertility." (PMID 38792459, 2024). "Moreover, NGF has shown promise in therapeutic applications for male infertility and related disorders." (PMID 38792459, 2024). "Indeed, the potential clinical applications of NGF in male infertility treatment have been discussed." (PMID 36361912, 2022). "Therefore, NGF might be exploited in male infertility treatment, suggesting potential new strategies for male infertility therapy." (PMID 36361912, 2022).
malnutrition (2 papers, 2019 to 2022). Inadequate nutrition resulting from poor diet, malabsorption, or abnormal nutrient distribution. "Full-length APP and its β-C-terminal fragment lead to nutritional deficiency of BFCNs by increasing activation of Rab5, which leads to early endosomal enlargement and disruption of retrograde nerve growth factor (NGF) signaling and axon transport." (PMID 35335180, 2022).
mastitis (2 papers, 2021 to 2024). Inflammation of breast tissue during lactation or postpartum due to an obstructed duct or infection. "Additionally, it has been shown that subclinical and clinical mastitis, as well as prior COVID-19 infection, reduce NGF levels in human milk." (PMID 39459341, 2024). "The impact of previous COVID-19 infection and mastitis on the concentration of BDNF and NGF in human milk was investigated." (PMID 33917718, 2021). "BDNF and NGF concentrations were comparable in milk from mothers with or without mastitis." (PMID 33917718, 2021).
Merkel cell carcinoma (2 papers, 2018 to 2021). "Among Merkel cell carcinoma, in a very interesting study 39 patients were analyzed for immunohistochemical PD-1, PD-L1 and nerve growth factor (NGF) expression." (PMID 34367064, 2021). "Basic fibroblast growth factor (bFGF), transforming growth factor-p1 (TGFp1), nerve growth factor (NGF), and epidermal growth factor (EGF) did not affect proliferation of Merkel cell carcinoma cells." (PMID 30895270, 2018).
metastasis (2 papers, 2006 to 2025). The spread or migration of cancer cells from one part of the body (where they first appeared) to another. "Strong NGF expression was associated with positive lymph node metastasis (P=0.005), positive distant metastasis (P=0.017), poorer tumour differentiation (P=0.033), and higher TNM staging (P=0.025)." (PMID 16832412, 2006). "Anti-NGF antibodies (e.g., tanezumab) demonstrated significant efficacy in alleviating bone metastasis-related pain in Phase III clinical trials, while potentially suppressing tumor growth via blockade of the NGF-TrkA signaling axis." (PMID 41142779, 2025).
Miscarriage (2 papers, 2015 to 2023). A pregnancy that ends at a stage in which the fetus is incapable of surviving on its own, defined as the spontaneous loss of a fetus before the 22th week of pregnancy. "In the placenta, NGF is involved in placentation and pregnancy maintenance, and has thus been implicated in stress-induced miscarriage and preterm birth." (PMID 25611484, 2015). "Thus, NGF signaling may have clinical relevance for miscarriage and preterm birth, as evidenced by animal and human studies." (PMID 25611484, 2015).